EGFR (epidermal growth factor receptor)
Diseases named in the same sentence as EGFR in open-access papers (continued):
Sharing a sentence is not in itself a finding about the gene and the disease.
lung cancer (continued). "A previous study in 12,833 Chinese lung cancer patients focusing on EGFR and ERBB2 has revealed a prevalence of 0.11 and 0.01% for germline mutations in the former and the latter, respectively." (PMID 33898318, 2021). "Taken together, targeting SREBP1-induced lipogenesis is a promising approach to overcome acquired resistance to gefitinib in EGFR-mutant lung cancer." (PMID 34775471, 2021). "To extend these findings and investigate the clinical relevance of PSAT1 in EGFR-mutant lung cancer, we analyzed microarray datasets from patients with EGFR-mutant lung tumors for a comparative expression analysis and correlation with clinical outcomes." (PMID 34439090, 2021). "In non‐small cell lung cancer (NSCLC), especially in adenocarcinoma, “driver mutations” have been discovered in genes such as EGFR (epidermal growth factor receptor), which are important to the processes of cancerization and proliferation." (PMID 33305905, 2021). "Several studies investigated the use of radiomic models in predicting EGFR status in patients with lung cancer." (PMID 34373989, 2021). "Exon 20 insertion mutants of EGFR, which show resistance to various FDA approved drugs and are linked to poor prognosis of lung cancer patients, were the primary focus of this study." (PMID 33530424, 2021). "For example, gefitinib, the epidermal growth factor receptor (EGFR) tyrosine kinase inhibitor (TKI) for advanced lung cancer, is the first EGFR-TKI drug." (PMID 33980216, 2021). "Recent studies revealed that ZEB1 contributes to the EMT‐mediated acquired resistance to gefitinib in EGFR‐mutant non‐small cell lung cancer (NSCLC)." (PMID 33764690, 2021). "The discovery of activating epidermal growth factor receptor (EGFR) mutations as the first targetable and predictive oncogenic driver alteration in lung cancer, has profoundly changed the diagnostic work-up and the therapeutic landscape of lung AC." (PMID 33671873, 2021). "We also assessed to what extent Rasarfin inhibited proliferation of A549 lung cancer cells, which have increased Ras and EGFR activity." (PMID 34344896, 2021). "MET amplification is more frequent in patients who smoke and in advanced tumor stage and solid predominant subtype of adenocarcinoma in patients with EGFR wildtype lung cancer." (PMID 34660325, 2021). "Since EGFRwt is expressed in the majority of NSCLC, a therapeutic targeting of this adaptive response would expand the use of EGFR inhibition to the majority of lung cancer." (PMID 34853306, 2021). "This has been successfully translated to practice in the treatment of many cancers including EGFR-driven lung cancers, BRAF-driven melanomas, Bcr-abl driven leukemias, and many other types of cancer." (PMID 33907275, 2021). "EGFR-TLI treatment of patients with KRAS mutations lacks efficacy, which indicates the different patterns of EGFR and KRAS gene mutations in lung cancer patients." (PMID 34217313, 2021). "EGFR gene evaluation has already become a key test in lung cancer management for prognosis and TKIs therapy election." (PMID 34503141, 2021). "The OS analysis in 1144 lung cancer patients revealed that the expression levels of PLK1 and EGFR mRNA and the OS rates were correlated inversely in human lung cancer (n = 1144, HR = 1.83, log rank P = 6.3 × 10−13)." (PMID 34503223, 2021). "On the other hand, an immune checkpoint inhibitor (ICI) has attracted great interest as a new treatment strategy for lung cancer patients and has been approved in EGFR‐TKI‐resistant NSCLC patients." (PMID 33305905, 2021). "Second, anti-EGFR-mAbs induce antibody-dependent cell-mediated cytotoxicity (ADCC) against EGFR-expressing lung cancer cells." (PMID 34964780, 2021). "The epidermal growth factor receptor (EGFR) plays an important role in cellular functions, and approximately 50% of lung cancer patients possess EGFR overactivated." (PMID 34299635, 2021).
lung cancer (continued). "At present, there is no report that ID1-mediated EMT promotes the formation of tumor stem cells to regulate the immune escape of EGFR T790M-positive lung cancer." (PMID 33992097, 2021). "Gefitinib, a selective EGFR inhibitor approved by the FDA for the treatment of lung cancer, consistently showed greater sensitivity in SNF5 knockdown BC cells." (PMID 34876150, 2021). "Here we describe a model of EGFR‐driven lung cancer and a method to develop tumors of distinct epigenetic states through the use of 3D organotypic cultures." (PMID 34622577, 2021). "Several combination therapies have been proposed for BRAF resistance in EGFR-mutant lung cancer, but an integrated genomic analysis of these tumors is lacking and precludes an optimization of therapeutic regimen." (PMID 34921211, 2021). "Considering the safety and feasibility of HDCAis for clinical applications, we verified two common HDACis, TSA, and SAHA in EGFR-WT lung cancer cells (A549 and H1299)." (PMID 33763356, 2021). "We believe that basal expression of ERK signaling is upregulated by mutant EGFR in lung cancer patients, but the addition of the hyperactive YAP can increase the ERK activity, and then upregulate the expression of p62." (PMID 33486901, 2021). "In the current study, we show that SREBP-1 mediated lipogenic pathway is a key mediator of oncogenic EGFR and that its constitutive activation contributes to gefitinib-acquired resistance in EGFR mutant lung cancer." (PMID 34775471, 2021). "EXOs include several tumor-related proteins in lung cancer, such as epidermal growth factor receptors (EGFR), KRAS, and extracellular metalloproteinase inducer." (PMID 34639135, 2021). "In lung cancer cells, the expression of EGFR and their ligands, especially transforming growth factor-alpha (TGFα), signifies the presence of a self-stimulatory (autocrine) growth factor loop." (PMID 34830377, 2021). "EGFR is overexpressed in most epithelial cell carcinomas such as colorectal cancer, breast cancer, and lung cancer, and it is known that activation of EGFR promotes cancer proliferation, angiogenesis, metastasis and inhibits apoptosis." (PMID 33946823, 2021). "In EGFR-mutant lung cancers obtained from patients who had developed resistance to TKIs, increased expression of AXL and, in some cases, its ligand GAS6 was observed." (PMID 34071428, 2021). "Recently, a novel DNA aptamer that binds selectively to Axl was shown to inhibit 30–40% cell growth and viability in human lung cancer cells with acquired resistance to EGFR-TKI." (PMID 33806258, 2021). "EGFR-targeted antibody therapies are being increasingly applied in cancer therapy since EGFR-tyrosine kinase activation is the main pathway mediating lung cancer progression." (PMID 33669950, 2021). "This leads to tumour initiation, anchorage-independent cell growth and resistance to EGFR inhibitors such as Erlotinib in pancreatic, breast and lung cancer." (PMID 34359657, 2021). "Here, we discovered that targeting cell cycle processes or protein ubiquitination pathways are promising treatment strategies for overcoming resistance to EGFR inhibitors in lung cancer using a genome‐scale CRISPR‐Cas9 screening." (PMID 33188726, 2021). "Compared to the TCGA data, the Nanjing Lung Cancer Cohort (NJLCC) and CHOICE cohort of Chinese patients revealed higher rates of EGFR and RB1 mutations, and lower rates of KRAS, BRAF, and STK11 mutations, in adenocarcinoma patients." (PMID 34195081, 2021). "Xie et al118 targeted lung cancer‐derived EVs expressing EGFR (A‐Exo) with EGFR‐targeting aptamers functionalized with mesoporous silica nanoparticles (MSNs)." (PMID 33145869, 2021). "A further retrospective trial using digital droplet PCR based performed analyses on archived tissue from 233 lung cancer patients treated with first-generation EGFR TKIs." (PMID 33869038, 2021).
lung cancer (continued). "Morgillo et.al studied the drug resistance related to IGFR/EGFR heterodimer on lung cancer cell lines and mice." (PMID 34112110, 2021). "As a close relative of BMP2, the upregulation of BMP4 has been proven to be strongly associated with EGFR-TKI resistance and fatty acid metabolism in lung cancer." (PMID 34745928, 2021). "Identification of specific EGFR mutation is critical in predicting response to TKI and successful lung cancer therapy." (PMID 35008242, 2021). "Many randomized, phase 3 studies have shown that for EGFR‐positive lung cancer patients, targeted drugs, such as gefitinib and osimertinib, can significantly prolong disease‐free survival and improve prognosis in patients." (PMID 34596344, 2021). "Compared with standard chemotherapy, the administration of TKI therapy that specifically targets EGFR to treat EGFR-mutant lung cancer can prolong PFS and improve the quality of life." (PMID 34054543, 2021). "Acquired resistance development is a major challenge in the epidermal growth factor receptor‐tyrosine kinase inhibitor (EGFR–TKI) treatment of non–small cell lung cancer (NSCLC)." (PMID 34510760, 2021). "The exploration of miRNA-dependent EGFR signaling that affects lung cancer cell behavior will essentially improve the design of a therapeutic modality for NSCLC." (PMID 34830377, 2021). "The TCGA lung cancer database analysis (N = 514) revealed that both EGFR/ERK2 (MAPK1) expression is significantly increased in patients with lung cancer, with a correlation coefficient value of 0.2508." (PMID 34885115, 2021). "This is evident from the effect of CDK9 inhibitors on both K-Ras mutant and EGFR mutant lung cancer cell lines." (PMID 34359807, 2021). "Dual inhibition of the vascular endothelial growth factor (VEGF) and epidermal growth factor receptor (EGFR) significantly improved the progression-free survival (PFS) of advanced EGFR-mutant non–small cell lung cancer (NSCLC)." (PMID 35046801, 2021). "To block cell survival via perturbing YAP‐p62 axis, we treated EGFR‐TKI‐resistant lung cancer cells with YAP inhibitor verteporfin." (PMID 33486901, 2021). "TGFβ1/integrin β3 axis has been proposed as an anticipating target for combination therapy in EGFR-mutant lung cancer." (PMID 35153741, 2021). "Here, we examine the role of STAT3 in TKI-resistance and choose gefitinib as a representative EGFR-TKI inhibitor in this study due to its wide application in lung cancer treatment." (PMID 33391507, 2021). "Lung cancer, especially NSCLC, has particularly high somatic mutations, including mutations in KRAS, EGFR and other surrogates, which share similar outputs at the downstream end of their signalling pathways." (PMID 34381028, 2021). "In EGFR-positive head and neck cancer and lung cancer cell lines, elevated expression of EGFR and PD-L1 levels occur concurrently." (PMID 34680249, 2021). "It was observed that EGFR (as well as its oncogenic mutants) and its signaling network proteins were commonly expressed in lung cancer exosomes from varying sources." (PMID 33855679, 2021). "In murine EGFR-driving lung cancer models, α-PD-1 effectively reversed T cell exhaustion and retarded tumor growth." (PMID 33413496, 2021). "Further studies are needed to demonstrate the clinical usefulness of T790M detection in sputum using ddPCR in patients with primary lung cancer undergoing EGFR-TKI treatment." (PMID 33757469, 2021). "Especially in lung cancer, various targeted therapies have been developed, ranging from EGFR-TKIs and BRAF, ALK, ROS, RET, MET, TRK1, and HER2 inhibitors, to more recent developments in KRAS inhibitors." (PMID 34359729, 2021).
lung cancer (continued). "Subsequently, we transfected miRNA‐1 (miR‐1), the most variable miRNA in this array, into three kinds of lung cancer cells, and examined the effects of miR‐1 on EGFR‐TKI sensitivity, cytokine expression and lymphocyte migration." (PMID 33305905, 2021). "We revealed that verteporfin is helpful to overcome the accumulation of p62 accompanied by autophagy inhibitor and the resistance of EGFR‐TKI in lung cancer." (PMID 33486901, 2021). "In lung cancer, A549 cell lines treated with EGFR-TKIA reduce cell viability via increment of IL-6 mRNA and protein expression." (PMID 34976811, 2021). "For instance, in 2014, a systematic multi-omic analyses on lung cancer have revealed a group of potential multi-omic biomarkers for lung cancer, including EGFR and CCT6A." (PMID 33767734, 2021). "Previously, it was revealed that EGFR activation is due to PD-L1 overexpression in lung cancers, and PD-L1 expression level can be reduced by EGFR-TKIs." (PMID 34830377, 2021). "The aqueous extract with identified bruceolide quassinoid mixture is effective against human lung cancer H1975 cells with double mutant EGFR." (PMID 35582384, 2021). "On the real sequencing reads dataset D0, we have performed instance-based error correction for the reads relevant to EGFR and KARS which are two genes highly associated with lung cancer." (PMID 34078284, 2021). "Another study found that approximately 80% of exosomes purified from lung cancer biopsies contained endothelial growth factor receptor (EGFR), which was present in only 2% of exosomes obtained from chronic lung inflammation samples." (PMID 34281588, 2021). "Risk factors for recurrence in early-stage epidermal growth factor receptor (EGFR)–positive non–small cell lung cancer (NSCLC) also remain undefined." (PMID 34739062, 2021). "In this study, we identified that lung cancer cells with EGFR‐TKI resistance activate autophagy in response to EGFR‐TKI and emphasized the effect of oncogenic p62, which is accumulated by autophagy inhibitor chloroquine." (PMID 33486901, 2021). "Based on our model and experience, it is recommended that when considering the use of EGFR-TKI in patients with spinal metastases from lung cancer." (PMID 34405024, 2021). "Although the mechanism of YAP-mediated EGFR-TKI resistance is not clear, the activation of YAP is capable of promoting EMT, leading to the induction of EGFR-TKI resistance in lung cancer." (PMID 33562150, 2021). "This includes the lung cancer cell line NCI-H1975 that has an EGFRT790M mutation, which is associated with resistance to first- and second-generation EGFR inhibitors." (PMID 33473169, 2021). "We previously showed that F+D produced synergy in EGFR mutant lung cancer cells, with enhanced blockade of the HER2/HER3 network." (PMID 35008514, 2021). "Despite the overall efficacy of EGFR tyrosine kinase inhibitors (TKIs) in lung cancer treatment, most patients develop TKI resistance within 8-10 months." (PMID 34680249, 2021). "An anticancer agent such as gefitinib, a tyrosine kinase inhibitor inhibiting receptor tyrosine kinase activity of EGFR, shows good efficacy for patients with EGFR mutant lung cancers, but drug resistance and metastatic properties can occur." (PMID 33925114, 2021). "Although metabolic differences were not clearly identified at the mRNA or protein level in glycolytic enzymes, the metabolic data indicate that glycolysis capacity was decreased in the lung cancer cells with acquired EGFR-TKI resistance." (PMID 34367462, 2021). "After the FLAURA trial reported practice changing outcomes with osimertinib in EGFR-mutant lung cancer, including patients with CNS involvement, osimertinib became an even more attractive agent to consider in patients with MGs with EGFR alterations." (PMID 35601813, 2021).
lung cancer (continued). "The epidermal growth factor receptor (EGFR), a member of the ErbB family, is expressed in a variety of cancers, including lung cancer, bladder cancer, and colorectal cancer, where it is associated with tumor progression and metastasis." (PMID 34040611, 2021). "For example, EGFR stimulation leads to c-Met phosphorylation and subsequent drug resistance in lung cancer that is reversed with dual c-Met and EGFR inhibitors." (PMID 34055785, 2021). "A good illustration is epidermal growth factor receptor (EGFR)/anaplastic lymphoma kinase (ALK) in lung cancer, CD19 in diffuse large B cell lymphoma and HER2 in breast cancer." (PMID 34872521, 2021). "The epidermal growth factor receptor, known as EGFR, is one of the most characterized genes in lung cancer and appears in around 10–35% of NSCLC patients." (PMID 34440110, 2021). "Lung cancer is often characterized by the presence of several oncogenes including mutant EGFR and K-ras." (PMID 34503236, 2021). "NF-ƙB activation has been associated with resistance to chemotherapeutics and tyrosine kinase inhibitors in EGFR mutant lung cancer." (PMID 35008645, 2021). "Over the years, oncogenic molecular alterations such as epidermal growth factor receptor (EGFR) were widely recognized in non‐small cell lung cancer (NSCLC) and contributed to clinical treatment." (PMID 34250747, 2021). "We previously demonstrated that RIT1M90I and other RIT1 variants, as well as KRASG12V, confer resistance to EGFR targeted therapy in EGFR-mutant lung cancer cells." (PMID 34373451, 2021). "Using an experimental in vivo mice model system, we present an assessment of the homing of EGFR mutant lung cancer cells to the lungs of the mice injected intravenously through the tail vein." (PMID 33993094, 2021). "Especially in the treatment of lung cancer, the main origin of brain metastases, several molecular markers such as EGFR, ALK, or PD1 can be exploited for targeted therapy approaches." (PMID 33883632, 2021). "NIR-PIT with panitumumab (another antibody targeting EGFR)-IR700 conjugates inhibited tumor growth in a transgenic mouse model of spontaneous lung cancer expressing human EGFR." (PMID 36405499, 2021). "Tyrosine kinase inhibitors (TKI) against EGFR, such as Gefitinib, are used as targeted therapy for lung cancer with EGFR gene changes, but many tumors acquire TKI resistance after treatment." (PMID 33946224, 2021). "We report a 65-year-old Japanese woman with nonsmall-cell lung cancer taking an EGFR-TKI who visited the emergency department with acute nausea and vomiting." (PMID 34306720, 2021). "Unpublished preclinical studies using xenograft mouse models have demonstrated the strong inhibitory activity of single-agent mefatinib on lung cancer harboring EGFR- or HER2-overexpression, or EGFR mutations." (PMID 34719670, 2021). "EGFR mutated stage IIIB and IV NSCLC patients diagnosed between January 2009 and December 2017 included in the Spanish Lung Cancer Group (SLCG) thoracic tumor registry." (PMID 34465283, 2021). "Recent evidence has revealed the role of HGF in transmitting resistance to epidermal growth factor receptor (EGFR) targeted therapy in lung cancer." (PMID 34095111, 2021). "Patients with EGFR-mutant lung cancer are commonly sensitive to receptor tyrosine kinase inhibitor (RTKi) drugs, which show some ability to improve overall survival." (PMID 34635780, 2021). "Given that CG antigens have been extensively investigated in melanoma, we have now described the CG antigen landscape in EGFR-mutant lung cancer, unveiling novel class I-presented peptides reported in our study." (PMID 34391887, 2021). "LLC mouse lung cancer cells were first transfected with EGFR-containing lentiviruses to activate EGFR signaling." (PMID 33537094, 2021). "RAS-PI3K interaction is an important signaling node and potential therapeutic target in EGFR-mutant lung cancer." (PMID 33505535, 2021).